MIR496 (microRNA 496)
Synonyms: hsa-mir-496; MIRN496; mir-496
Gene: MicroRNA gene on chromosome 14 (101,060,573 to 101,060,674, forward strand). Ensembl gene ENSG00000207961.
Gene Ontology:
Biological process: miRNA-mediated post-transcriptional gene silencing
Cellular component: RISC complex
Homologues: Orthologues: chimpanzee ptr-mir-496 (100% identical), macaque mml-mir-496 (99% identical), dog MIR496 (90% identical), guinea pig MIR496 (72% identical), rat Mir496 (71% identical), mouse Mir496a (70% identical). Paralogues in human: MIR323B (56% identical), MIR494 (54% identical), MIR539 (54% identical), MIR323A (53% identical), MIR410 (52% identical), MIR487A (51% identical), MIR154 (49% identical), MIR1185-1 (48% identical), MIR487B (48% identical), MIR656 (48% identical), MIR1185-2 (46% identical), MIR382 (46% identical), and 4 more.